SEZ6 (seizure related 6 homolog)
Description:
May play a role in cell-cell recognition and in neuronal membrane signaling. Seems to be important for the achievement of the necessary balance between dendrite elongation and branching during the elaboration of a complex dendritic arbor. Involved in the development of appropriate excitatory synaptic connectivity (By similarity).
Synonyms: BSRPC
Tractability: Antibody: UniProt places it where antibodies can reach, with medium confidence; UniProt predicts a signal peptide or a membrane-spanning region; its Gene Ontology location is reachable by antibodies, with medium confidence. PROTAC: its protein half-life has been measured.
Gene: Protein-coding gene on chromosome 17 (28,954,901 to 29,006,440, reverse strand). Ensembl gene ENSG00000063015.
Subcellular location: Cell membrane
Gene Ontology:
Molecular function: protein binding
Biological process: regulation of dendrite development; synapse maturation; adult locomotory behavior; cerebellar Purkinje cell layer development
Cellular component: dendritic shaft; dendritic spine; endoplasmic reticulum; neuronal cell body; apical dendrite; perinuclear region of cytoplasm; plasma membrane
Genetic constraint (gnomAD): Loss-of-function variants: 53 observed, 94.13 expected, observed/expected ratio (o/e) 0.56, 90% interval 0.45 to 0.71. The upper end of that interval is the gene's LOEUF score, 0.71, which puts it in group 2 of 6, group 1 being the genes least tolerant of losing a copy. Missense variants: 1,095 observed, 1,256.7 expected, observed/expected ratio (o/e) 0.87, 90% interval 0.83 to 0.92. Synonymous variants: 481 observed, 498.23 expected, observed/expected ratio (o/e) 0.97, 90% interval 0.89 to 1.04.
Homologues: Orthologues: chimpanzee SEZ6 (99% identical), macaque SEZ6 (98% identical), guinea pig SEZ6 (92% identical), rabbit SEZ6 (91% identical), dog SEZ6 (91% identical), mouse Sez6 (91% identical), rat Sez6 (90% identical), pig SEZ6 (87% identical), tropical clawed frog sez6 (57% identical), zebrafish sez6b (50% identical), zebrafish sez6a (45% identical). Paralogues in human: SEZ6L (41% identical), SEZ6L2 (41% identical), CSMD2 (22% identical), CSMD3 (21% identical), CSMD1 (21% identical), SVEP1 (17% identical), CR1 (13% identical), CFB (12% identical), CR2 (11% identical), C2 (11% identical), C4BPA (10% identical), CFH (10% identical), and 27 more.
Diseases named in the same sentence as SEZ6 in open-access papers:
SEZ6 is named in the same sentence as 42 diseases in open-access papers, as found by Europe PMC text mining. Sharing a sentence is not in itself a finding about the gene and the disease. The quoted sentences say what the papers report.
Alzheimer disease (6 papers, 2016 to 2025). A progressive, neurodegenerative disease characterized by loss of function and death of nerve cells in several areas of the brain leading to loss of cognitive function such as memory and language. "Altered SEZ6 levels in cerebrospinal fluid are also linked to neuropsychiatric and neurodegenerative disorders, including Alzheimer’s disease." (PMID 34958451, 2022). "There are multiple reported common variants in SEZ6 which have been linked to diseases such as febrile seizure, epilepsy, Alzheimer’s disease and schizophrenia." (PMID 34664540, 2022). "Seizure protein 6 (SEZ6) is required for the development and maintenance of the nervous system, is a major substrate of the protease BACE1 and is linked to Alzheimer's disease (AD) and psychiatric disorders, but its molecular functions are not well understood." (PMID 32567721, 2020). "Finally, we successfully verified significantly lower levels (p<0.05) of eight proteins (A2GL, APOM, C1QB, C1QC, C1S, FBLN3, PTPRZ, and SEZ6) in Alzheimer’s disease compared to controls using an antibody-based detection method." (PMID 26950848, 2016).
epilepsy (6 papers, 2011 to 2022). A brain disorder characterized by episodes of abnormally increased neuronal discharge resulting in transient episodes of sensory or motor neurological dysfunction, or psychic dysfunction. "SEZ6 gene mutations have been also reported in association with febrile seizures, and SEZ6 was proposed as a candidate gene for epilepsy." (PMID 30309378, 2018). "SEZ6 has been genetically linked to febrile seizures and epilepsy, whereas SEZ6L was associated with bipolar disorder." (PMID 27716410, 2016). "SEZ6 warrants further investigation as a susceptibility gene for both febrile seizures and the epilepsies which show complex inheritance." (PMID 21785725, 2011). "Moreover, mutations in the human SNc stable gene SEZ6 have been implicated in diseases such as Alzheimer’s, childhood-onset schizophrenia, epilepsy and febrile seizures." (PMID 34305528, 2021).
schizophrenia (4 papers, 2018 to 2022). A major psychotic disorder characterized by abnormalities in the perception or expression of reality. "This reveals a novel molecular function for the transmembrane protein SEZ6, which is linked to schizophrenia and AD, but is also required for nervous system development, synaptic connectivity, and LTP." (PMID 32567721, 2020). "Genetic variants of SEZ6 are linked to childhood‐onset schizophrenia (Thr229‐Thr231del), intellectual disability (Arg657Gln), and AD (Arg615His)." (PMID 32567721, 2020). "Moreover, SEZ6 mutations were found in cases of childhood-onset schizophrenia." (PMID 30309378, 2018). "Soluble Sez6 is elevated in the CSF of patients with schizophrenia, bipolar, major depression and inflammatory pain compared to controls." (PMID 33936031, 2021). "For example, deletions in the SEZ6 ectodomain are found in childhood‐onset schizophrenia." (PMID 32567721, 2020).
bipolar disorder (2 papers, 2016 to 2022). A disorder of the brain that causes unusual shifts in mood, energy, activity levels and the ability to carry out day-to-day tasks. "Additional studies have also linked homologs of SEZ6, such as SEZ6L, to bipolar disorder." (PMID 34664540, 2022).
childhood-onset schizophrenia (2 papers, 2016 to 2021). "The Sez6 gene is highly conserved between mice and humans, and sez6 mutations and/or altered expression has been associated with febrile seizures, autism spectrum disorder, intellectual disability and childhood-onset schizophrenia." (PMID 27456313, 2016).
cognitive deficits (2 papers, 2019 to 2022). "For BACE 1 inhibitors, it has been suggested that the synaptic plasticity via seizure protein 6 (SEZ6) is a possible reason for cognitive impairment." (PMID 31787864, 2019). "In fact, mice lacking all three SEZ6 family members (SEZ6 triple knockout (KO) or TKO mice) have motor coordination deficits on the rotarod and cognitive deficits." (PMID 34958451, 2022).
depression (2 papers, 2021 to 2022). "Lastly, due to the inherent rarity of the variation being studied, we acknowledge that for the SEZ6 rs117736100 locus we report very low counts of severe depression cases and alternative alleles observed, resulting in the variant falling short of significance after correction for multiple testing." (PMID 34664540, 2022).
febrile seizures (2 papers, 2011 to 2017). "Studies using mouse primary neurons associated Sez6 with pentylenetetrazol-induced bursting activity, an attribute of neurons undergoing epileptic discharges Sez6 mutation is also associated with febrile seizures in children." (PMID 28899353, 2017).
Intellectual disability (2 papers, 2016 to 2020). "Other genetic variants have been reported in intellectual disability, while the rare SEZ6 mutation R615H has been suggested to cause a familial form of AD." (PMID 32567721, 2020).
neuroendocrine neoplasm (2 papers, 2023 to 2025). Endocrine tumors, also referred to as neuroendocrine tumors (NETs), are defined by a common phenotype which is characterized by the expression of general markers (neuron specific enolase, chromogranin, synaptophysin) and hormone secretion products. "SEZ6 (Seizure-related 6 homolog), a membrane-associated protein, has also been identified neuroendocrine neoplasms (NENs)." (PMID 40699376, 2025). "In conclusion, this study provides a comprehensive overview of DLL3 and SEZ6 expression in the spectrum of neuroendocrine neoplasms, revealing distinct patterns across different tumor types and grades." (PMID 40699376, 2025). "Seizure related 6 homolog (SEZ6) is a cell surface protein that has been found to be highly expressed in neuroendocrine tumors with minimal expression in the majority of normal tissues which makes it another potential target for SCLC." (PMID 37627044, 2023). "We examined a series of NENs of all types as well as several non-neuroendocrine neoplasms using immunohistochemistry for DLL3 and SEZ6." (PMID 40699376, 2025). "Two well-differentiated grade 2 thymic neuroendocrine tumors had positive staining for both DLL3 and SEZ6, with moderate intensity in about 10% of cells for DLL3 (H-score 20 for both), and 20% strong and 40% moderate positivity of cells for SEZ6 (average H-score 70, range 60–80)." (PMID 40699376, 2025). "In 43 non-neuroendocrine neoplasms of the GI tract, pancreas, and liver and 10 non-neuroendocrine thyroid carcinomas, there was only weak focal reactivity for DLL3 in three and two cases, respectively, and for SEZ6 in one case each." (PMID 40699376, 2025).
Anxiety (1 paper, 2022). Intense feelings of nervousness, tension, or panic often arise in response to interpersonal stresses. "Future studies should further investigate the role of SEZ6L in anxiety-related behaviour and identify whether SEZ6L KO mice have enhanced fear learning, as identified in SEZ6 TKOs." (PMID 34958451, 2022). "In contrast, results from the elevated open field are comparable in SEZ6L KO and SEZ6 TKO mice, suggesting that SEZ6L deletion is contributing to the anxiety-like phenotype previously reported in SEZ6 TKO mice (which was also manifest in the zero maze, not examined in this study)." (PMID 34958451, 2022).
dementia (1 paper, 2023). Loss of intellectual abilities interfering with an individual's social and occupational functions. "Within these genes, through proteomic study, BAG3 may affect AD by influencing the interpretation of Aβ and tau protein, and patients with AD have much lower levels of SEZ6 in their cerebrospinal fluid than those without dementia." (PMID 37867597, 2023).
gastric NETs (1 paper, 2025). "One of 13 gastric NETs, a metastatic grade 3 tumor, expressed both DLL3 and SEZ6 (H-score 200 for each) and one other expressed SEZ6 at lower levels." (PMID 40699376, 2025).
hepatocellular carcinoma (1 paper, 2025). A malignant tumor that arises from hepatocytes. "One steatohepatitic hepatocellular carcinoma was moderately positive for SEZ6 in 5% of the tumor cells (H-score 10)." (PMID 40699376, 2025).
injury (1 paper, 2022). Damage inflicted on the body as the direct or indirect result of an external force, with or without disruption of structural continuity. "SEZ6, an active regulated mRNA transcript, is indispensable for the development of dendrites and synapses, and involving in the development of chronic hyperalgesia and neuroinflammation following nerve injury." (PMID 36581948, 2022).
interstitial lung disease (1 paper, 2026). A diverse group of lung diseases that affect the lung parenchyma. "Beyond DLL3, next-generation ADCs targeting TROP2, B7-H3, and SEZ6 have reported encouraging early-phase activity, including response rates exceeding those of existing second-line cytotoxic options, though myelosuppression, interstitial lung disease, and hepatic toxicity remain key considerations." (PMID 41562777, 2026).
medullary thyroid carcinomas (1 paper, 2025). "Both DLL3 and SEZ6 were expressed in medullary thyroid carcinomas (10 of 11 cases, H-scores 199 for DLL3 and 224 for SEZ6)." (PMID 40699376, 2025). "SEZ6 expression was more variable across different NEN types but was consistent and strong in medullary thyroid carcinoma as previously reported." (PMID 40699376, 2025).
Merkel cell carcinomas (1 paper, 2025). "Merkel cell carcinomas (n = 13) expressed DLL3 strongly and diffusely (H-score 178, range 10–300) and 10 of 13 had positivity for SEZ6 (H-score 128)." (PMID 40699376, 2025).
metastatic disease (1 paper, 2025). "The biological significance of SEZ6 expression in these tumors warrants further investigation, but this common occurrence offers opportunities for novel approaches to the treatment of patient with refractory recurrent or metastatic disease." (PMID 40699376, 2025).
multiple sclerosis (1 paper, 2025). A progressive autoimmune disorder affecting the central nervous system resulting in demyelination. "SEZ6 has been found be elevated in the CSF from patients with multiple sclerosis and inflammatory conditions, furthermore, has been shown to promote metastatic spread by affecting cellular adhesion, cytoskeletal and extracellular matrix remodeling and inducing EMT in cancer cells." (PMID 40342827, 2025).
oncocytic adenoma (1 paper, 2025). A benign neoplasm composed of large cells with abundant eosinophilic granular cytoplasm. "We examined five parathyroid adenomas, including a lipoadenoma, a chief cell adenoma, an oncocytic adenoma, and two clear cell adenomas; all these tumors were negative for both DLL3 and SEZ6." (PMID 40699376, 2025).
pancreatic NECs (1 paper, 2025). "DLL3 was positive in two pancreatic NECs (H-score 197), and SEZ6 was positive in 1 (H-score 60)." (PMID 40699376, 2025). "Pancreatic NECs (n = 2) showed strong DLL3 positivity (50–98% of cells) (average H-score 200), and one case had strong SEZ6 expression in 20% of the tumor cells (H-score 60)." (PMID 40699376, 2025).
paraganglioma (1 paper, 2025). A benign or malignant neoplasm arising from paraganglia located along the sympathetic or parasympathetic nerves. "Three of 20 paragangliomas expressed DLL3 weakly (H-score 43), and six expressed SEZ6 (H-score 73)." (PMID 40699376, 2025).
parathyroid adenomas (1 paper, 2025). "One of four parathyroid carcinomas expressed DLL3 weakly (H-score 30), and all four were negative for SEZ6; five parathyroid adenomas were negative for both." (PMID 40699376, 2025).
small cell lung carcinoma (1 paper, 2025). Small cell lung cancer (SCLC) is a highly aggressive malignant neoplasm, accounting for 10-15% of lung cancer cases, characterized byrapid growth, and early metastasis. "SEZ6 expression was seen in one large-cell NEC with weak positivity in 70% of cells (H-score 70) and not in small-cell lung carcinoma." (PMID 40699376, 2025).
thymic neuroendocrine tumor (1 paper, 2025). Thymic endocrine tumor is a rare, malignant, primary thymic neoplasm originating from neuroendocrine cells, presenting as a mass within the anterior mediastinum. "Two thymic neuroendocrine tumors (NETs) had weak expression of DLL3 (H-score 20) and SEZ6 (H-score 70)." (PMID 40699376, 2025).
thyroid carcinomas (1 paper, 2025). "Among the 10 thyroid carcinomas, only two poorly differentiated oncocytic carcinomas were weakly positive in 10% of the cells for DLL3 (H-score 10), and only one of those tumors was moderately positive for SEZ6 in 5% of the cells (H-score 10)." (PMID 40699376, 2025).
viral infection (1 paper, 2022). "These four molecules are characteristic of each subtype, including: SEZ6 for autoimmune subtype, SPOCK3 for inflammation, FSD1 for viral infection, and PGC for oxidative stress." (PMID 36713418, 2022).
tumor (4 papers, 2021 to 2025). "ADCs represent a promising class of therapeutics for SCLC, driven by the selective overexpression of target antigens such as DLL3, B7-H3, TROP-2 and SEZ6 in tumour tissue, which provides a clear rationale for their use." (PMID 41463450, 2025). "We found that the expressions of CCL1, FABP7, S100B, CTSW, and SEZ6 significantly decreased in the tumor tissue, the expression of CPLX2 and SPIB increased obviously in BC." (PMID 36581948, 2022). "Among six corticotroph tumors that included two densely granulated, three sparsely granulated, and one Crooke cell tumor, two were positive for DLL3 and three for SEZ6." (PMID 40699376, 2025). "Tumor microenvironment related genes ADGRG7, CSN3, CST8, KRT81, MUC7, MYH6, and SEZ6 are valuable predictors for HNSCC patient survival." (PMID 33530209, 2021). "SEZ6 expression in ileal NETs was overall weaker, with and average H-score of 78 (range 30–160) and did not correlate with tumor grade." (PMID 40699376, 2025). "While G3 tumors were more frequently positive and had stronger positivity, there was no strict correlation between tumor grade and SEZ6 reactivity." (PMID 40699376, 2025). "Functional analysis of ADGRG7, CST8, and SEZ6 in tumor biology has not been reported." (PMID 33530209, 2021). "Among these eight tumors, six expressed DLL3 focally and weakly and seven expressed SEZ6; interestingly, the aggressive immature PIT1-lineage tumor was negative for DLL3 but expressed SEX6 diffusely (H-score 200)." (PMID 40699376, 2025).
psychiatric diseases (2 papers, 2018 to 2020). "SEZ6 is linked to neurological and psychiatric diseases, but the underlying molecular mechanisms are little understood." (PMID 32567721, 2020). "For instance, seizure-related gene 6 (SEZ6) has been reported in brain development and psychiatric disorders and is differentially expressed in the cerebrospinal fluid of AD cases." (PMID 30309378, 2018). "This novel function may help to better understand the role of SEZ6 in neurologic and psychiatric diseases." (PMID 32567721, 2020). "Interestingly, besides SEZ6 mutations, also changes in HNK‐1 metabolism may contribute to psychiatric diseases." (PMID 32567721, 2020).
adenocarcinoma (1 paper, 2025). A common cancer characterized by the presence of malignant glandular cells. "The only NEC positive for SEZ6 was a poorly differentiated adenocarcinoma with variable neuroendocrine differentiation; it was strongly positive for DLL3 and was also moderately positive for SEZ6 in 20% of the cells (H-score 40)." (PMID 40699376, 2025).
lung (1 paper, 2025). "Nine of 11 lung NETs expressed DLL3 (H-score 191), while only two had focal weak staining for SEZ6 (H-score 45)." (PMID 40699376, 2025).
neurodevelopmental disorder (1 paper, 2024). A behavioral and cognitive disorder with onset during the developmental period that involves impaired or aberrant development of intellectual, motor, or social functions. "Some of these genes themselves are of interest in brain development specifically, Nipa2 (non-imprinted in Prader-Willi/Angelman syndrome 2), Sez6 (seizure-related 6 homologs), and Aff4 (AF4/FMR2 family member 4) are involved in neurodevelopmental disorders with complex phenotypes." (PMID 37059894, 2024).
neurologic diseases (1 paper, 2020). "Genetic variants of SEZ6 are linked to psychiatric and neurological disorders." (PMID 32567721, 2020). "Given the genetic link of SEZ6 to psychiatric and neurologic diseases, the new function and mechanism of action for SEZ6 are also of major relevance for understanding these devastating diseases." (PMID 32567721, 2020).
SEZ6 also shares sentences with these, for which no sentence is quoted: cancer (3 papers); Seizure (2); autism spectrum disorder (1); cholangiocarcinoma (1); colonic adenocarcinoma (1); Niemann-Pick type C disease (1); nonsyndromic hearing impairment (1); parathyroid carcinomas (1).